IGFBP5 (insulin like growth factor binding protein 5)
Diseases named in the same sentence as IGFBP5 in open-access papers (continued):
Sharing a sentence is not in itself a finding about the gene and the disease.
tumor (continued). "In the past 30 years, studies of IGFBP5 have mainly focused on the regulatory mechanisms of kidney, bone, and mammary gland physiological processes and the regulation of specific tumor proliferation." (PMID 35282347, 2022). "IGFBP5 overexpression in an orthotopic xenograft inhibited tumor growth and pulmonary metastasis while siRNA mediated silencing enhanced pulmonary metastasis after cell injection into the tibia." (PMID 36465383, 2022). "Over-expression of IGFBP5 inhibits cell proliferation and primary tumor growth and induces apoptosis." (PMID 36465383, 2022). "IGFBP5 overexpression increases the progression to androgen independence in subcutaneous tumors in nude mice after castration, and IGFBP5 silencing with antisense oligodeoxynucleotides reduced proliferation in Shionogi tumor cells." (PMID 36465383, 2022). "By inhibiting or promoting IGF1R signaling, IGFBP5 can either act as a tumor suppressor or promoter." (PMID 36093095, 2022). "One proposed explanation for this phenomenon is the interaction of the tumor cells with cells of the tumor microenvironment via the Insulin-like growth factor RNA binding protein 5/B-cell lymphoma 3 (IGFBP5/BCL3) axis." (PMID 35020071, 2022). "IGFBP5 mRNA-negative samples have elevated expression of miR-140-5p. miR-140-5p expression is increased in tumor tissue relative to normal tissue." (PMID 36465383, 2022). "Specifically, IGFBP3 was reported to inhibit tumorigenesis and cell growth, and IGFBP5 was suggested to function as a tumor suppressor." (PMID 35688943, 2022). "Morphologically, SRF and IGFBP5 were present in the diffuse-type tumor cells, with some overlap with MRTFA+ cells." (PMID 35087207, 2022). "It remains to be shown to what extent IGFBP5 contributes to their tumor-suppressing or tumor-promoting activities in BC." (PMID 36093095, 2022). "The involvement of IGFBP5 in all these various pathways to neoplasia illustrate the importance of this protein, and indeed this family of proteins, in regulating the development and progression of cancer." (PMID 36465383, 2022). "The result identified the oncogenic activity of TMEM16A in GIST and involved the regulation of IGF/IGFR signaling in the tumor microenvironment via antiangiogenic factor IGFBP5." (PMID 33681289, 2021). "In cancer, IGFBP5 is characterized as an inhibitor of angiogenesis, contributing to tumor suppression." (PMID 34830489, 2021). "The presence of IGFBP5, a tumor suppressor, in circulating sEV, suggests its discharge from cells, likely favoring tumor progression." (PMID 34439311, 2021). "In 96 tumours investigated by high‐coverage exome sequencing, we detected missense mutations in: IGF1R (n = 1), IGF2R (n = 1) and IGFBP5 (n = 2)." (PMID 33295144, 2021). "Mechanistically, DIRC3 seems to promote expression of the tumor suppressor IGFBP5 through a chromatin loop, which brings both genes into close proximity." (PMID 33329688, 2020). "Many studies have shown that IGFBP5 can suppress tumor proliferation and metastasis, while others have shown that IGFBP5 can function as an oncogene to promote tumor metastasis." (PMID 32127912, 2020). "Accumulating evidence has revealed that IGFBP5 can suppress tumor growth and metastasis in various tissues and under different contexts, but IGFBP5 can also function as an oncogene, promoting metastasis in a context-dependent manner." (PMID 32801999, 2020). "High LAT1 expression was associated with advanced pT stage (P = 0.0001), tumour grade (P = 0.0001), high neutrophil-to-lymphocyte ratio (NLR) (P = 0.0007), high LDH (P = 0.0017), and high IGFBP-5 score (P = 0.0001) among BC patients." (PMID 31992742, 2020).
tumor (continued). "DIRC3 therefore appears to act through IGFBP5 to regulate growth in soft agar and exert its tumour suppressor effect." (PMID 31881017, 2019). "The type of changes found for some genes belong to the well-known mechanism of downregulation of tumour suppressors through promoter DNA hypermethylation, which was the case of Oat and Igfbp5 that can act as tumour suppressors in certain cellular contexts." (PMID 30089774, 2018). "In our study, we also discovered abnormal expression of some tumor suppressor genes, such as IGFBP5 and SFN, which high expressed in the Mcfips, but low in Hips." (PMID 28423718, 2017). "We found that peptides containing the heparin-binding domain derived from the C-terminus of IGFBP-5 inhibited angiogenesis and tumor growth by regulation of the Akt/ERK and NF-kB–VEGF/MMP-9 signaling pathway in an IGF-independent manner." (PMID 28008951, 2016). "As each domain of IGFBP-5 performs different functions, we investigated which domain is responsible for the inhibition of tumor growth." (PMID 28008951, 2016). "In conclusion, the C-terminus of IGFBP-5 exerts a tumor suppressive function, probably by inhibiting angiogenesis." (PMID 28008951, 2016). "We therefore tested the effect of the three domains of IGFBP-5 on tumor growth and demonstrated that the C-terminal domain had a tumor suppressive function and that its overexpression inhibited VEGF-A expression and the Akt/ERK–NF-kB signaling pathway." (PMID 28008951, 2016). "Tumor characteristics and fold changes of IGFBP5 expression in patients for use in microarray analysis." (PMID 26569312, 2015). "Using this stable IGFBP5 overexpression (OE) cell line, we assessed the effects of IGFBP5 on cell proliferation and tumor growth using CCK-8 assay and colony formation assay." (PMID 26010068, 2015). "In contrast, IGFBP5 tumor tissue levels have been found to be significantly associated with poor disease outcome and the addition of IGFBP4 (measured as IGFBP5/IGFBP4 ratio expression levels) further increased prognostic power." (PMID 25743390, 2015). "To explore the effects of IGFBP5 on MM progression, we conducted a series of tumor migration and invasion assays in vitro with stably transfected A375 OE cells and in vivo in xenograft mice." (PMID 26010068, 2015). "Together, these data substantially demonstrate that IGFBP5 functions as a tumor suppressor for melanoma tumor growth." (PMID 26010068, 2015). "Many preclinical studies indicate that IGFBP5 can suppress tumor growth and metastasis in various tissues and contexts, but IGFBP5 can also function as an oncogene, promoting metastasis in a context-dependent manner." (PMID 26010068, 2015). "IGFBP5 levels were detected to be upregulated in 21 (55.3%) and downregulated in 17 (44.7%) tumor samples compared to their adjacent normal tissues." (PMID 26569312, 2015). "The authors of this study further suggested that part of the mechanism for IGFBP-5 in reducing tumor volume after acute treatment with the Wnt pathway inhibitor was due to down-regulation of IGF-1R signaling." (PMID 26106366, 2015). "The functional and clinical meaning of expressional differences of IGFBP5 in tumor tissue is still controversial." (PMID 26569312, 2015). "Remarkably, IGFBP5 inhibited tumor growth in IGFBP5 OE mice significantly (mean tumor weight: 0.018 ± 0.008 g, *, p < 0.05), whereas the tumors of the control group grew far larger (mean tumor weight: 1.73 ± 0.46 g)." (PMID 26010068, 2015).
tumor (continued). "cDNA microarrays were applied to the highest IGFBP5 overexpressed tumor samples compared to their adjacent normal breast tissue." (PMID 26569312, 2015). "The same study showed over-expression of IGFBP-5 in MCF-7 xenografts inhibited tumor development in mice." (PMID 26569312, 2015). "The mechanism of IGFBP5 as a regulator of the oncogenic receptor ligands IGF-I and -II is well understood, but there are relatively few studies demonstrating the involvement of IGFBP5 in the signaling pathways that regulate tumor growth and metastasis." (PMID 26010068, 2015). "IGFBP5 is one of the family members of IGF-binding proteins which play a critical role in tumor progression, especially cell survival, death and metastasis processes." (PMID 26569312, 2015). "Consistent with IGFBP5 overexpression results, down-regulation of IGFBP5 promoted cell proliferation and tumor growth significantly." (PMID 26010068, 2015). "Igfbp5 is of particular interest, in that it is expressed focally at the tumor epithelial-stromal interface." (PMID 25242334, 2014). "One of the tumor suppressors down-regulated by PIWIL1 is IGFBP-5, which we have previously shown to be an interacting partner of RASSF1C." (PMID 25007054, 2014). "Our previous study identified that curcumin activates p38/MAPK, which brings about C/EBPα up-regulation and IGFBP-5 induction; these effects result in tumor suppression in OSCC." (PMID 25229239, 2014). "Recent studies show that over-expression of PIWIL1 promotes sarcomagenesis and down-regulates a number of tumor suppressors, including insulin-like growth factor binding protein 5 (IGFBP-5)." (PMID 25007054, 2014). "Transcriptional and protein analyses showed that FGFR1 (P = 0.006 and P<0.01, respectively) and IGFBP5 (P = 0.0002 and P = 0.006, respectively) were up-regulated in the tumours when compared with the adjacent normal myometrium." (PMID 23483937, 2013). "Several candidate genes, such as MYCN, ERBB3, JUN, and IGFBP5, were also significantly upregulated, which keeps the tumor in a proliferative state." (PMID 22690114, 2012). "Tumor growth and tumor vascularity were decreased in the presence of IGFBP-5 expression in a xenograft model of human ovarian cancer." (PMID 21197468, 2011). "Conversely, a reduction in TFF3 (or an increase in IGFBP5) following tamoxifen treatment in vivo and the protein levels in primary tumors correlated with a reduction in tumor volume in the 28 patients treated with tamoxifen for three months." (PMID 20569502, 2010). "The change in IGFBP5, TFF3 or both was significantly associated with change in tumor volume (P = 0.0135, 0.018 and 0.0002, respectively; Spearman rank test)." (PMID 20569502, 2010). "In primary cancer cells in tumor tissues, IGFBP5 is mainly located in the cytoplasm, whereas in cell culture, exogenously introduced IGFBP5 is mainly localized in the nucleus using its nuclear localization signal." (PMID 19341485, 2009). "In addition to that, IGFBP-5 has been identified in the literature as a binding protein with proliferation-suppressing properties and is known to have anti-tumor effects." (PMID 41303367, 2025). "Instead, we analyzed patient material and single cell data to explore the hypothesis that IGFBP5 from neighboring stromal cells and the malignant cells sculptures the tumor microenvironment." (PMID 40234830, 2025). "Interestingly, tumor-expressed HIF-1 regulates skeletal muscle wasting via promotion of IGFBP-5 expression." (PMID 41226289, 2025). "This suggests that even if non-malignant mesenchymal stromal induce IGFBP5 expression in RMS cells, their own secretion of IGFBP5 may contribute even more to local enrichment of IGFBP5 in the tumor microenvironment." (PMID 40234830, 2025). "Since IGFBP5 is reported as a direct transcriptional target of HIF1α, it may serve as a feedback mechanism for tumours to inhibit IGF1R signalling in adjacent normal cells." (PMID 38886900, 2024).
tumor (continued). "All these results suggest that IGFBP5 may promote tumor metastasis via recruiting infiltration of macrophages and leading to development of immune-suppressive tumor environment." (PMID 38164271, 2024). "Finally, we showed that IGFBP5 can be employed as an effective therapeutic target using a nanocapsule-based platform to decrease tumor progression and improve the survival rate." (PMID 36949068, 2023). "Thus, it is conceivable that IGFBP5 expression is dynamic and potentially acting as a switch that can either aid or inhibit tumor progression, depending on factors such as promoter methylation." (PMID 36465383, 2022). "Stromal cell populations in the tumor, such as fibroblasts, are also responsible for IGFBP5 secretion, and study of fibroblast-induced changes in IGFBP5 expression in the TME could be informative in the context of epithelial-to-mesenchymal transition (EMT)." (PMID 36465383, 2022). "In this case, IGFBP5 would have a dual effect in BC, suppressive in the initial phase by its pro-apoptotic activity and promoting in the late phase of tumor development by supporting the metastatic activity of the tumor." (PMID 36093095, 2022). "The data indicating that increased IGFBP5 is correlated with decreased overall survival in ovarian, breast and other cancers contrasts with the many in vitro and in vivo studies suggesting a tumor-suppressor function." (PMID 36465383, 2022). "Tumor growth and vascularity were decreased with IGFBP5 overexpression in a subcutaneous xenograft." (PMID 36465383, 2022). "The factors (IGFBP5, CLCF1 and IL6) reported to be secreted by CAFs indeed showed significantly higher expression in the high-risk group, suggesting that fibroblasts in the tumor microenvironment of LUAD likely contribute to the poor outcome in LUAD patients." (PMID 35711936, 2022). "Additionally, single-cell sequencing revealed that IGFBP5 was enriched in pancreatic circulating tumors cells (CTCs) compared to bulk tumor." (PMID 36465383, 2022). "In addition to the large body of evidence that indicates IGFBP5 acts as a tumor suppressor, there is considerable evidence that it has oncogenic roles." (PMID 36465383, 2022). "There is evidence that IGFBP5 partially mediates this tumor-suppressive effect." (PMID 36093095, 2022). "PKNOX2 positively regulates IGFBP5 expression in vitro and in vivo by acting as a tumor suppressor." (PMID 36465383, 2022). "IGFBP5 knockdown via siRNA indicating Cisplatin resistance in ESCC cells, and thereby upregulation of IGFBP5 could play an important role in promoting sensitivity of tumor cells to chemotherapeutic agents." (PMID 33768092, 2021). "However, other studies showed that IGFBP5 played a positive role in tumor progression by promoting tumor cell survival and migration." (PMID 34362467, 2021). "In addition, we found that TUG1 knockdown inhibited the tumorigenesis of HemECs in vivo, accompanied by miR-137 upregulation and IGFBP5 downregulation in tumor tissues." (PMID 34362467, 2021). "IGFBP5 and Ki-67 levels in tumor tissues were confirmed by Western blot." (PMID 34362467, 2021). "In addition, a slightly increased expression (more than 2-fold) of EPHA5 and IGFBP5 was detectable at the edge of the tumor compared with the center." (PMID 32872409, 2020). "With regards to the dormancy phenomenon and the slightly increased expression of the dormancy markers EPHA5 and IGFBP5 at the edge of the tumor observed in our study, the only connection published to date is an induction of MCT4 and dormancy markers by hypoxia." (PMID 32872409, 2020). "Moreover, it was observed that DIRC3 depletion induces an increased SOX10 (SRY-box transcription factor 10) repression of IGFBP5 in melanoma cell cultures, corroborating the tumor suppressor role of DIRC3." (PMID 33218058, 2020). "Based on these findings, we hypothesized that tumor suppressive effect of PKNOX2 in GC might be mediated by IGFBP5." (PMID 30745575, 2019).
tumor (continued). "Moreover, cell viability and colony formation assays revealed that IGFBP5 silencing abrogated the tumor suppressive effect of PKNOX2 in AGS cells overexpressing PKNOX2, suggesting that tumor suppressive function of PKNOX2 in GC cells was dependent on IGFBP5." (PMID 30745575, 2019). "We next assess if IGFBP5 has a tumor suppressive role in GES1 cells that express endogenous PKNOX2." (PMID 30745575, 2019). "Recent studies have demonstrated a tumor suppressor role of IGFBP5." (PMID 30745575, 2019). "IGFBP5 thus operates as a tumor suppressor in GC cells expressing PKNOX2." (PMID 30745575, 2019). "This might explain why VEGF-A expression and tumor growth were inhibited only in 2774 cells stably expressing the C-terminus of IGFBP-5." (PMID 28008951, 2016). "We investigated the functional significance of IGFBP-5 as a tumor suppressor." (PMID 28008951, 2016). "This suggests that IGFBP5 may act as a tumor suppressor disturbing a wide array of signaling pathways." (PMID 26010068, 2015). "Overexpression of IGFBP5 was more common in patients with advanced tumor grades (p = 0.0123)." (PMID 26569312, 2015). "Therefore, we propose that IGFBP5 suppresses tumor growth and metastasis, including EMT, through the MEK-ERK and p38-MAPK signaling pathways." (PMID 26010068, 2015). "Especially, IGFBP-3 and IGFBP-5 show their tumor suppressor character in HNSCC." (PMID 25880247, 2015). "Recent evidence also indicates that Igfbp5 may act as a tumour suppressor by inhibiting angiogenesis." (PMID 20459814, 2010). "These were Defcr4, S100A9, Igfbp5, Slc30a2 and Lgr5 (leucine-rich repeat containing G protein coupled receptor 5) which were up-regulated and Mptx, Slc26a3, Retnla, Muc2 and Hpgd (hydroxyprostaglandin dehydrogenase 15) which were down-regulated in tumours." (PMID 20459814, 2010). "IGFBP-5 has also been shown to play an important role in regulating tumor growth." (PMID 19476635, 2009). "Compared with the presurgical levels, serum levels of TYMS-AAb, IGFBP5-AAb, and HAPLN1-AAb decrease at 3 months after surgery and remain low up to one year, implying a possibility of utilizing CMT-associated AAbs for predicting tumor recurrence or treatment responses." (PMID 36139323, 2022). "Therefore it may be speculated that induction of IGFBP-5, which is pro-apoptotic in some cancers, may be an important function of miR-193 downregulation in tumor suppression." (PMID 35597813, 2022). "Interestingly, IGFBP5 expressing CTCs were localized at the epithelial-stromal boundary, indicating that the stromal cells surrounding the tumor may be involved in modulating the expression of IGFBP5." (PMID 36465383, 2022). "Hence, there must be additional, tumor-promoting IGFBP5 activities, which have yet to be uncovered." (PMID 36093095, 2022). "Besides, this strategy shed light on the fact that upregulation of IGFBP5 through employing lentivirus in POU2F3high SCLC lines could suppress tumor cell growth remarkably." (PMID 33768092, 2021). "IGFBP-5 also enhances adhesion of MCF-7 cells to mesenchymal cell derived matrix and may play a role in the inhibition of epithelial-mesenchymal transition (EMT) a process closely associated with tumour cell development and metastasis." (PMID 27050076, 2016). "However, overexpression of IGFBP5 in A375 cells led to a cobblestone morphology in monolayer cultures with tight cell-cell contacts, characteristic of normal epithelial cells, indicating that IGFBP5 most likely reversed tumor cell EMT." (PMID 26010068, 2015). "VARGG accurately reveals the spatial organization of tumors and identifies key genes related to tumor progression and immune microenvironment (VEGFA, CD74, SPP1, IGFBP5, TIMP2, EMP1, THY1)." (PMID 41275376, 2025).